OR10AG1 (olfactory receptor family 10 subfamily AG member 1)
Description:
Odorant receptor.
Synonyms: OR11-160
Tractability: Antibody: UniProt places it where antibodies can reach, with medium confidence; UniProt predicts a signal peptide or a membrane-spanning region; its Gene Ontology location is reachable by antibodies, with medium confidence.
Gene: Protein-coding gene on chromosome 11 (55,965,755 to 55,969,945, reverse strand). Ensembl gene ENSG00000174970.
Subcellular location: Cell membrane
Pathways (Reactome):
Sensory Perception: Expression and translocation of olfactory receptors
Gene Ontology:
Molecular function: protein binding; olfactory receptor activity; G protein-coupled receptor activity
Biological process: detection of chemical stimulus involved in sensory perception of smell; G protein-coupled receptor signaling pathway
Cellular component: plasma membrane; membrane
Genetic constraint (gnomAD): Missense variants: 344 observed, 320.89 expected, observed/expected ratio (o/e) 1.07, 90% interval 0.98 to 1.17. Synonymous variants: 119 observed, 110.77 expected, observed/expected ratio (o/e) 1.07, 90% interval 0.93 to 1.25.
Homologues: Orthologues: chimpanzee OR10AG1 (88% identical), rabbit OR10AG1 (76% identical), dog OR10AG1 (75% identical), mouse Or10ag2 (72% identical), rat Or10ag54b (71% identical), mouse Or10ag56 (71% identical), rat Or10ag54 (70% identical), mouse Or10ag54 (70% identical), mouse Or10ag55 (69% identical), mouse Or10ag57 (68% identical), rat Or10ag57 (68% identical), guinea pig OR10AG1 (65% identical). Paralogues in human: OR10A5 (46% identical), OR10A4 (46% identical), OR10A7 (45% identical), OR10P1 (45% identical), OR2G3 (45% identical), OR2S2 (45% identical), OR10A2 (45% identical), OR10C1 (45% identical), OR13C4 (44% identical), OR5V1 (44% identical), OR10A3 (44% identical), OR10H2 (44% identical), and 80 more.